SLC7A11 (solute carrier family 7 member 11)
Diseases named in the same sentence as SLC7A11 in open-access papers (continued):
Sharing a sentence is not in itself a finding about the gene and the disease.
glioma (continued). "This firstly revealed the effects of OTUB1 on glioma stemness and provided a novel mechanism by which SLC7A11 protein, a critical suppressor of ferroptosis, is regulated in glioma cells." (PMID 34927544, 2021). "All in all, these results demonstrate that OTUB1 knockdown reduces glioma stemness dependent on SLC7A11 expression." (PMID 34927544, 2021). "In solid tumors, SLC7A11 was observed to express highly in the malignant cells of glioma, while for SKCM, SLC7A11 was highly expressed in immune cells and moderately expressed in malignant and stromal cells." (PMID 34938318, 2021). "Ectopic expression of SLC7A11 has been shown to be a marker of poor glioma survival and confer chemoresistance in human glioma." (PMID 34927544, 2021). "Taken together, this work identifies a novel OTUB1/SLC7A11 axis contributing to glioma cell stemness." (PMID 34927544, 2021). "Accumulating evidence demonstrated that SLC7A11 played importantly in the progression and the survival of different carcinoma cell types, including breast, glioma, and lymphoma." (PMID 34722314, 2021). "The toxicity of TMZ to glioma cells is correlated to the expression of SLC7A11, and ferroptosis would enhance this effect of TMZ." (PMID 32656078, 2020). "This correlation is of significance given that SLC7A11 overexpression found in glioma cells has been shown to promote the growth of the brain tumors." (PMID 31273299, 2020). "SLC7A11, which function as cystine/glutamate antiporter, was also highly expressed and enhances the stemness phenotype of glioma stem cells (GSCs)." (PMID 31885621, 2019). "SLC7A11 (xCT) is a glutamate/cystine antiporter highly expressed in glioma cells, where it was identified as a key-driver in glutamate release." (PMID 30716120, 2019). "We monitored cell survival, ATF4 mRNA expression of ATF4 and xCT (SLC7a11) regulation within human gliomas." (PMID 28881638, 2017). "We first tested the glutamate-cystine antiporter xCT/SLC7a11/system xC- in DEXA-responsive glioma cells." (PMID 24714627, 2014). "For instance, the PI3K/AKT signaling activation could induce SLC7A11 expression, leading to treatment resistance in glioma." (PMID 39870645, 2025). "Additionally, the expression of xCT/SLC7A11 in patient glioma tissue correlates with the peritumoral glutamate response to sulfasalazine, suggesting its potential as a predictive biomarker for the efficacy of sulfasalazine in modulating glutamate release." (PMID 40076738, 2025). "Furthermore, elevated xCT/SLC7A11 expression correlates with increased extracellular glutamate, neuronal toxicity, and reduced overall survival in glioma patients." (PMID 40076738, 2025). "The upregulation of disulfidptosis related genes SLC3A2 and SLC7A11 promotes the occurrence and progression of glioma tumors, therefore, a signal target of disulfidptosis may be used in the therapeutic schedule for neurogliomas." (PMID 40109666, 2025). "In addition, these findings provide a mechanistic explanation for a previous observation that administration of the SLC7A11 inhibitor erastin diminished angiogenesis in glioma." (PMID 38610018, 2024). "Moreover, a proteomic analysis implies that Bach1 (BTB and CNC homology 1), highly expressed in gliomas, accelerates tumor invasion while conversely confers enhanced vulnerability to ferroptosis, possibly due to altered SLC7A11 expression." (PMID 39309434, 2024). "To better understand this finding, we first verified if murine glioma cells expressed Slc7a11." (PMID 39192032, 2024). "Assessments combining iron levels, gene expression, and mutations might help identify patients who would benefit most from ferroptosis, such as those with gliomas overexpressing SLC7A11 being potential targets for SLC7A11 inhibitors." (PMID 38322268, 2024).
glioma (continued). "Insights into glutamatergic interactions in glioma are increasing: GBM cells express high levels of SLC7A11solute carrier family 7 member 11or xCT, a subunit of xc-cystine-glutamate transporter system, which acts as a cystine/glutamate antiporter across the plasma membrane." (PMID 36831117, 2023). "In addition, the overexpression of SLC7A11 in glioma cells improves their resistance to oxidative stress and decreases their sensitivity to temozolomide." (PMID 37799714, 2023). "Moreover, studies have shown that increased SLC7A11 levels contributed to the malignant progression and unfavorable prognosis of glioma." (PMID 38162649, 2023). "Furthermore, it was found that the activation of EGFR can enhance the expression of SLC7A11 in glioma cells, thereby enhancing the transport activity of system Xc−, resulting in ferroptosis resistance." (PMID 37580745, 2023). "SLC7A11 has been found to be involved in approximately 50% of glioma patient tumors." (PMID 35280777, 2022). "Several studies have documented that glioma cells upregulate the expression of SLC7A11 (xCT)." (PMID 36072803, 2022). "Moreover, SLC7A11, as a key suppressor of ferroptosis, has been reported to play a role in inhibiting ferroptosis in glioma and OC." (PMID 35311457, 2022). "SLC7A11-mediated glutamate release promotes glioma cell infiltration and could be blocked by xCT inhibitors such as sulfasalazine and (S)-4-carboxyphenylglycine." (PMID 36552652, 2022). "GSH depletion and SLC7A11 downregulation have been observed in glioma cells after SHK treatment." (PMID 36387145, 2022). "SLC7A11 overexpressing U251 glioma cells exhibit actin cytoskeletal changes reminiscent of epithelial-like cells and display an increased CSC-like phenotype, which might cause tumor drug resistance and recurrence." (PMID 36072803, 2022). "The mechanisms by which SLC7A11 protein was regulated are revealed in glioma." (PMID 34927544, 2021). "Notably, activation of the Nrf2/Keap1 pathway increases xCT (SLC7A11) expression and diminishes ferroptosis, thus facilitating glioma cell growth." (PMID 34098867, 2021). "SLC7A11, which is overexpressed in various tumors, is closely related to glioma progression." (PMID 34927544, 2021). "This study provides a potential target for glioma treatment by targeting the OTUB1/SLC7A11 axis." (PMID 34927544, 2021). "Notably, ectopic expression of SLC7A11 attenuated the inhibition of OTUB1 knockdown on the stemenss of glioma cells." (PMID 34927544, 2021). "SLC7A11 was overexpressed in glioma cells with OTUB1 knockdown." (PMID 34927544, 2021). "Studies have shown that glioma patients with a high expression of ATF4 have a shorter survival time, and ATF4 can inhibit the ferroptosis of glioma cells by regulating the expression of the downstream gene SLC7A11, in order to promote tumor proliferation and angiogenesis." (PMID 32656078, 2020). "However, suppressing the SLC7A11 expression can enhance the sensitivity of gliomas to TMZ using siRNA." (PMID 32656078, 2020). "In addition, over-expression of SLC7A11 increased resistance to oxidative stress and decreased chemosensitivity to temozolomide in the context of glioma." (PMID 30558624, 2018). "It has been evidenced that SLC7A11 has oncogenic functions in glioma." (PMID 30558624, 2018). "In our study, the high expression of SLC7A11 suggests that patients had longer OS, suggesting that disulfidptosis involved in SLC7A11 may play an important role in glioma, which also provided a theoretical hypothesis for further study of disulfidptosis in glioma." (PMID 39993959, 2025). "Overexpression of xCT (SLC7A11) has been hypothesized to play an important role in the increase of ambient non‐synaptic Glu levels and the development of a hyperexcitable peritumoral network leading to glioma‐associated epileptic discharges and excitotoxicity." (PMID 40197808, 2025).
glioma (continued). "PRMT1 promotes ferroptosis by suppressing key antioxidant systems, including solute carrier family 7-member 11 (SLC7A11), and its inhibition could provide dual therapeutic benefits—enhancing neuroprotection while improving treatment responses in conditions like gliomas." (PMID 40951640, 2025). "Oppositely, enhanced IRF2 in gliomas may interfere with SLC7A11 and GPX4 to extinguish ferroptosis." (PMID 39309434, 2024). "A study of glioma cells showed that knockdown of SLC7A11 increased ROS production and decreased glutathione production, resulting in increased cell death under oxidative and genotoxic stress, and overexpression of SLC7A11 leads to increased resistance to oxidative stress." (PMID 36935924, 2023). "However, expression levels of EAAT2 are vastly reduced in gliomas, which combined with increased efflux via the glutamate/cystine antiporter (xCT, SLC7A11) leads to elevated glutamate levels surrounding the glioma that induce cell death and allow further growth of the tumor." (PMID 38074092, 2023). "Additionally, high cell density in glioma cells promotes lysosomal degradation of SLC7A11, which may enable metabolic adaptation and cell survival." (PMID 36552652, 2022). "Three criteria, including iron levels, gene expression and mutations, can be combined to assess which patients are most likely to benefit from ferroptosis; for example, SLC7A11 inhibitors may be particularly effective against certain types of gliomas that overexpress this target." (PMID 36358495, 2022). "Epidermal growth factor receptor (EGFR) was shown to interact with SLC7A11 protein to maintain its localization at the cell membrane; increased cystine uptake and enhanced glutamate export associated with tumor growth and invasiveness has been observed in EGFR-expressing glioma cells." (PMID 35280777, 2022). "Then we speculated that OTUB1 can regulate the ferroptotic process through SLC7A11 in glioma cells." (PMID 34927544, 2021). "Additionally, co-IP analysis indicated that OTUB1 directly interacted with SLC7A11 in glioma cells." (PMID 34927544, 2021). "Finally, we wondered whether SLC7A11 is responsible for OTUB1 knockdown-induced effects on glioma stemness." (PMID 34927544, 2021). "Moreover, abnormal expression of SLC7A11, regulated by IR, has been reported recently; high expression was found to correspond to poor survival in patients diagnosed with glioma, whereas SLC7A11 methylation indicated increased overall survival and disease-free survival." (PMID 34249928, 2021). "Thus, this work demonstrates that the OTUB1/SLC7A11 axis could be a potential target for glioma progression." (PMID 34927544, 2021). "Thus, this work identifies a novel OTUB1/SLC7A11 axis contributing to glioma cell stemness." (PMID 34927544, 2021). "MMP7 codes for a metastatic promoting protein, HERC5 is an ubiquitin ligase that may be involved in malignancy, SLC7A11 is a part of the anionic amino acid transport system and was highly expressed in early stages of glioma, and LPHN2 has a role in cell adhesion." (PMID 26515461, 2016). "GYS1, NDUFA11, OXSM, RPN1, and SLC3A2 play a role in promoting cancer in glioma, while LRPPRC, NCKAP1, NDUFS1, NUBPL and SLC7A11 play a role in inhibiting tumour." (PMID 39993959, 2025). "Conversely, NF-κB pathway activation in GPX4 knocked-down glioma cells decreased ATF4 and SLC7A11 expression and significantly increased the occurrence of ferroptosis." (PMID 38539832, 2024). "Ferroptosis, a recently popular topic, has made great progress in the treatment of glioma, and its regulators Erastin, RSL3, RAS, and SLC7A11 have been studied in glioma." (PMID 38304870, 2024). "In gliomas, the non‐vesicular secretion of glutamate through the cystine–glutamate exchanger (SLC7A11, xCT) is the primary mechanism responsible for the elevated concentration of extracellular glutamate." (PMID 38641945, 2024).
glioma (continued). "To assess the role of CIRBP in ferroptosis, we analyzed its effect on erastin-induced and ferrostatin 1-inhibited ferroptosis in glioma cells and expression of GPX4 and SLC7A11, which are markers of ferroptosis." (PMID 39857625, 2024). "For instance, it has been discovered to promote ferroptosis in NSCLC by modulating SLC7A11/GPX4, and it can induce ferroptosis in glioma cells by the ACSL4/GPX4 pathway, thus providing antitumor benefits." (PMID 39266965, 2024). "Ex vivo slices from human gliomas showed both synergistic sensitivity to CMD and ferroptosis inducers as well as significant transcriptional upregulation of CHAC1 and SLC7a11 following CMD." (PMID 36864031, 2023). "The glioma cells treated with T4O showed a significant reduction in the expression of the negative regulators of ferroptosis, GPX4, COX2, SLC40A1, and SLC7A11." (PMID 37375197, 2023). "ATF4 promotes the expression of GSH and SLC7A11 to avoid ferroptosis in glioma cells, inhibition of ATF4 can reduce the resistance of glioma cells to TMZ." (PMID 36072803, 2022). "EGFR-expressing glioma cells exhibit increased glutamate export, cystine uptake, and GSH biosynthesis, while targeted inhibition of SLC7A11 suppresses the antioxidant capacity, growth, and invasion of EGFR-overexpressing cancer cells." (PMID 36552652, 2022). "In conclusion, we demonstrated that glioma resistance to SAS-induced ferroptosis was enhanced by hypoxia, owing to the activation of the PI3K/AKT/HIF-1α pathway and promotion SLC7A11 expression." (PMID 36439690, 2022). "Mechanistic studies revealed that OTUB1 stabilized SLC7A11 protein via directly interacting with SLC7A11 and OTUB1 knockdown triggered ferroptosis of glioma cells." (PMID 34927544, 2021). "In glioma cells, the C-terminus of EGFR directly interacts with the central part of Slc7a11 and stabilizes Slc7a11 cell surface expression, thereby suggesting a role in oncogenic signaling." (PMID 32587657, 2020). "In brief, these findings indicate that ATF4 can affect glioma ferroptosis and TMZ resistance by regulating the expression of SLC7A11." (PMID 32656078, 2020). "SLC7A11, the catalytic subunit responsible for SXC-induced glutamate release, was also found to be greatly elevated in glioma patients with epileptic activity." (PMID 26967053, 2016). "Although previous studies have reported SLC7A11 (xCT) and BCAT1 as potential biomarkers for glioma-associated seizures, our dataset did not reveal significant mutation frequencies in these genes." (PMID 40718831, 2025). "Remarkably, SLC7A11 was also one of the related hub genes of SLC3A2, which reinforced the conclusion that SLC3A2 may interact with gliomas through disulfidptosis." (PMID 38977800, 2024). "Notably, regulatory proteins such as SLC7A11 and NCKAP1, critical in disulfidptosis, also play essential roles in glioma onset and progression." (PMID 38504986, 2024). "In the present investigation, we found that SLC39A14 silencing may promote erastin-induced ferroptosis in glioma by modulating the levels of MDA, Fe2+, GSH, GPX4, NRF2, and SLC7A11, which may further inhibit the progression of gliomas." (PMID 37978473, 2023). "Given the known effect of OTUB1 on SLC7A11 and the critical role of SLC7A11 on ferroptosis, we next investigated whether the OTUB1-dependent effects of glioma cell stemness could be explained within such context." (PMID 34927544, 2021).
glioma (continued). "To further support the notion that ATF3 represses SLC7A11 expression, we analyzed publicly available gene expression datasets and found that the ATF3 expression level inversely correlated with the SLC7A11 level in two cohorts of glioma patients." (PMID 31273299, 2020). "Moreover, inhibition of glutamate release via system Xc−, consisting of xCT (SLC7A11) and CD98 (SLC3A2, 4F2HC), profoundly decelerates the glioma phenotype in vivo, and in addition mitigates tumor-induced brain swelling and tumor-induced seizures." (PMID 27074570, 2016). "The cystine/glutamate transporter (xCT or SLC7A11) is critical for L-cystine influx into the cell--then reduced to cysteine for glutathione synthesis, redox metabolism, and energy balance, particularly in hypoxic gliomas." (PMID 24039668, 2013). "However, the pathways related to SLC7A11 expression were not related to hypoxia induction directly in glioma." (PMID 36439690, 2022). "The CCK-8 cell viability assay showed that SLC7A11 knockdown could not influence the proliferation rate of glioma cells." (PMID 36439690, 2022). "As an example, OTUB1, a deubiquitinating enzyme overexpressed in gliomas, regulates SLC7A11, a critical inhibitory molecule in the ferroptosis Xc-system, directly through the ubiquitinase-proteasome degradation system, forming the OTUB1/SLC7A11 axis and thus promoting the stemness of glioma cells." (PMID 36091118, 2022). "Notably, Activating Transcription Factor 3 (ATF3) enhances glioma cell ferroptosis by promoting hydrogen peroxide and iron accumulation, whereas Activating Transcription Factor 4 (ATF4) triggers ferroptosis through Solute Carrier Family 7 Member 11 (SCL7A11)/SCX-dependent mechanism." (PMID 39857625, 2024). "Lastly, the dependency on GPX4 yet not SLC7A11 in both mouse models may suggest that glioma cells obtain cysteine independent of the system xc− antiporter, such as the transsulfuration pathway, while still depending on robust GPX4 activity to eliminate lethal concentrations of lipid peroxides." (PMID 39192032, 2024).